IL1B (interleukin 1 beta)
Diseases named in the same sentence as IL1B in open-access papers (continued):
Sharing a sentence is not in itself a finding about the gene and the disease.
depression (continued). "We reported that the IL-1β level at baseline was positively correlated with the severity of depression at middle-term follow-up." (PMID 38459460, 2024). "Increased cytokines that initiate the inflammatory cascade, such as interleukin-1 Beta (IL-1β), IL-6, and tumor necrosis factor (TNF), have been associated with severe depression linked to stress." (PMID 39335507, 2024). "Specifically, cytokines such as IL-1β, IL-6, and TNF-α, associated with depression, can induce thermoregulatory abnormalities leading to fever and HFs14." (PMID 39019875, 2024). "The study explored the correlation between pro-inflammatory cytokines such as TNFα, IL-1β and IL-6 with hippocampal volume and scores on the Beck Depression Inventory." (PMID 38377025, 2024). "The elevated levels of certain cytokines are associated with inflammation in the brain, including interleukin-1 beta (IL-1β), interleukin-6 (IL-6), and tumor necrosis factor-alpha (TNF-α), which has been linked to the pathophysiology of depression." (PMID 39513898, 2024). "For example, a recent study evaluated levels of the NLRP3 inflammasome and IL-1β in patients with MI and depression." (PMID 39590595, 2024). "There is a great deal of correlational evidence that patients who suffer from anxiety and depression show elevations in circulating levels of cytokines that are pro-inflammatory in nature, such as Tumor necrosis factor alpha, IL-1β, IL-6, and IL-17." (PMID 38255692, 2024). "It has been shown that patients with major depressive disorders had increased inflammatory markers such as interleukin (IL)-1β, IL-6, tumor necrosis factor (TNF)-α and C-reactive protein (CRP)." (PMID 39394060, 2024). "The experimental findings have also indicated that the CD-1 mice subjected to the administration of interleukin-1beta (IL-1β) and LPS contributed to depression-like effects in the tail suspension test (TST) and the forced swim test (FST)." (PMID 37917302, 2024). "It is important to remember that the “cytokine theory of depression” proposes that enhanced production of proinflammatory cytokines (such as IL-6, IL-1β, IFN-γ, and TNFα) is associated with the pathogenesis of depression." (PMID 38731995, 2024). "Activation of NLRP3 and increased secretion of IL-1β and IL-18 are essential pathophysiological mechanisms of depression." (PMID 38627683, 2024). "Depression can result in elevated levels of C-reactive protein, interleukin (IL)-1β, IL-6, and tissue necrotic factor-alpha, as well as an increase in the concentration of inflammatory molecules, such as NLRP3 inflammasomes." (PMID 39006364, 2024). "Given the high prevalence of depression in this patient population, this study sought to explore the potential influence of IL‐1β genetic variations on the severity of depressive symptoms." (PMID 37937732, 2024). "Evidence indicates that injecting TNF-α into the hippocampus can lead to depressive-like behaviors, while IL-1β also promotes depression onset, highlighting the role of central inflammatory factors in depression." (PMID 39595861, 2024). "Maternal infection, anxiety, or depression are associated with increased levels of pro-inflammatory cytokines, including TNF-α, IL-1β, and IL-6, not only in the maternal circulation but also in the fetal circulation and CNS." (PMID 38726788, 2024). "Individuals with depression, for instance, frequently show elevated levels of pro-inflammatory cytokines—such as IL-1β, IL-6, and TNF-α—in their blood and cerebrospinal fluid." (PMID 39273641, 2024). "Polymorphisms in genes such as IL-1β, IL-6, IL-10, TNF, MCP1/CCL2, CRP, and phospholipase A2 are among the most consistently observed findings in major depressive disorder." (PMID 39723161, 2024). "In depression, the excessive production of IL-1β negatively impacts the body’s inflammatory response and can hasten the progression of TB." (PMID 38742123, 2024).
depression (continued). "Patients with severe depression and animal models of depression often exhibit elevated levels of pro-inflammatory cytokines such as IL-1β, IL-6, and TNF-α." (PMID 38628641, 2024). "The IL-4 effects on microglia also show benefit in depression where infusion of IL-4 alleviated IL-1β induced depressive behaviours in rats." (PMID 39526037, 2024). "TNF-α, IL-1β and IL-6 promote depression and inhibit the functional activity of serotonergic neurons." (PMID 38898454, 2024). "In ovariectomised mice, forced treadmill exercise for one week was found to reduce depression-like behaviours (as observed in a sucrose preference test and a forced swim test) by reducing IL-1β and IL-18 levels in the hippocampus." (PMID 38560580, 2024). "The M1 phenotype leads to a chronic neuroinflammatory reaction, induces the release of proinflammatory cytokines such as TNF-α and IL-1β, exacerbates tissue damage, and further aggravates the pathological process of depression." (PMID 38337722, 2024). "Increased inflammatory cytokines in the brain and in serum, such as CRP, and soluble cell-adhesion molecules IL-6, IL-1β, TNF-α and NF-κB, would be involved in the susceptibility to depression in stressed obese mice." (PMID 37836393, 2023). "Elevated plasma levels of IL-1β have been observed in patients with depression, and this cytokine is an efficient stimulator of the hypothalamic–pituitary–adrenal axis (HPA)." (PMID 37692303, 2023). "Activated inflammasomes and IL-1β, IL-6, and IL-18 play important roles in regulating major depressive disorders." (PMID 37868345, 2023). "Pearson correlations between anxiety-/depression-/cognition deficit-like behaviors and the levels of inflammatory factors (IL-1β, TNF-α, and IL-6) in the hippocampus [r (p)]." (PMID 37560531, 2023). "High levels of IL-1β and IL-18 deplete synaptic serotonin, dopamine and norepinephrine, contributing to depression, particularly anhedonia." (PMID 37206541, 2023). "The concentrations of proinflammatory cytokines, like TNF-α, IL-1β and IL-6 were significantly higher in UC patients with symptoms of anxiety/depression." (PMID 36906523, 2023). "The impact of pro-inflammatory cytokines such as TNF-α, IL-1β, IL-6, and IL-8 on depression has been widely studied." (PMID 38025419, 2023). "It suggests that IL-1β plays a pivotal role in both the disruption of sleep and the manifestation of depression." (PMID 37692303, 2023). "Patients with depression exhibit an increased expression of proinflammatory cytokines and their receptors in the peripheral blood and cerebrospinal fluid (CSF), especially IL-1β, IL-6 and TNF-α, as the cardinal feature of the inflammatory responses." (PMID 36838809, 2023). "One possible reason for this difference is that IL-1β has pleiotropic effects due to its cellular localization and different stages of depression." (PMID 37600668, 2023). "Among the two IL-1 s, however, the role of IL-1β appears to be more relevant, particularly in relation to anxiety and depression." (PMID 37693246, 2023). "Secondary outcomes to be assessed are the severity of co-morbid depression and anxiety symptoms; the serum levels of IL-1β, IL-6 and TNF-α; changes in ERP and fecal microbiota content." (PMID 38051740, 2023). "The NLRP3/IL-1β pathway of microglia in the ACC of AR mice is involved in the pathological process of anxiety and depression-like behavior, and the loss of TET2 further activates the NLRP3/IL-1β pathway of microglia in AR mice." (PMID 38012545, 2023). "Patients with GC and CC genotypes of rs1143623 (IL1B-1560G/ C) demonstrated different levels of disease severity as evaluated by the Hamilton Depression Rating Scale." (PMID 37510364, 2023).
depression (continued). "After 3-week CMS exposure, our data showed that IL-1β reduced the anti-depression effect of PHL in OFT, SPT, and FST." (PMID 36793870, 2023). "Elevated levels of IL-1β and IL-6 are related to the severity of depression throughout the prenatal and postnatal periods." (PMID 37239199, 2023). "TET2 deficiency activates the NLRP3/IL-1β pathway of microglia in the ACC, promoting the pathological process of anxiety and depression-like behavior in AR." (PMID 38012545, 2023). "IL-1β mRNA in the hippocampus of the post-stroke depression is significantly increased, and the content of GABA in the lateral hypothalamic area is decreased." (PMID 37369673, 2023). "Maternal immune activation was shown to result in anxiety- and depression-like behaviors, cognitive impairment, and increased levels of proinflammatory cytokines, including interleukin (IL)-1β, IL-6, and tumor necrosis factor-alpha (TNF-α) in offspring." (PMID 37560531, 2023). "Subsequently, anxiety- and depression-like behaviors and spatial learning and memory function were evaluated in the offspring, as were the hippocampal levels of markers of inflammation (IL-1β, IL-6, TNF-α) and synaptic function (PSD-95, SYN)." (PMID 37560531, 2023). "The high levels of inflammatory cytokines such as TGF-β, TNF-α, and IL-1β in the peripheral blood of patients with depression fully indicate that inflammation is related to depression." (PMID 37868345, 2023). "In particular, after childhood abuse, men carrying the rs16944*GG of IL1B showed particularly severe symptoms of depression." (PMID 37510364, 2023). "Major depressive disorder (MDD) has been linked to inflammation, including significant increases in chemokines and cytokines including IL-1α, IL-1β, and IL-6." (PMID 37239169, 2023). "We aimed to correlate the DC-TMD and QoL findings with the salivary levels of mediators that play a relevant role in pain, depression, and anxiety, specifically IL-1β, glutamate, and serotonin." (PMID 37471347, 2023). "Increased inflammatory markers were measured in patients with major depressive disorder: IL-1β, IL-6, TNF-α, and CRP." (PMID 36899845, 2023). "Some studies have reported increased interleukin-1β (IL-1β) and interleukin-6 (IL-6) and decreased IL-4 and IL-10 in patients with depression." (PMID 37139495, 2023). "Recent findings have shown that the higher the level of IL-1β in peripheral blood, the worse the cognitive function of patients with depression." (PMID 37165444, 2023). "IL-1β was significantly increased in the sera of patients with depressive disorder, showing a positive correlation with depression’s severity." (PMID 37628746, 2023). "By analyzing 41 cytokines using the largest available GWAS datasets, we identified that a potential causal relationship between IL-18, IL-1β, and RANTES and depression." (PMID 37600668, 2023). "Other studies have reported strong associations between depression symptoms and circulating levels of TNF and IL-1β." (PMID 38299049, 2023). "The aim of this study was to investigate the effects of probiotics on cognitive function and the regulation of cortisol and IL-1β in adolescents with depression." (PMID 37763233, 2023). "Some researchers have found activation of microglia and increased expression of the pro-inflammatory cytokine IL-1β in the amygdala, an important brain region regulating emotional and pain responses, in a rat model of depression." (PMID 38023826, 2023). "Activation of NLRP3 inflammasome was linked to the pathophysiology of different cardiovascular diseases and neurological diseases including depression by promoting the cleavage of pro-IL-1β to produce mature IL-1β." (PMID 36781714, 2023). "The level of IL-1β in peripheral blood of patients with depression is much higher than that of normal people." (PMID 37165444, 2023). "The treatment normalized brain levels of IL-1β, TNFα, and IFNγ which were higher in depression models." (PMID 37240605, 2023).
depression (continued). "It is believed that inflammation plays a role in the development of depression, and statins have been shown to reduce the expression of hippocampal pro-inflammatory cytokines such as IL-1β, TNF-α, and IL-6." (PMID 37599890, 2023). "Supporting this, increased levels of proinflammatory cytokines including IL-1β and IL-6 and decreased levels of anti-inflammatory cytokines including IL-4 and IL-10 have been detected in people living with depression." (PMID 38053532, 2023). "In elderly patients with depression, IL-1β is abnormally elevated in patients who are resistant to antidepressants." (PMID 36838809, 2023). "Associations between polymorphic variants of the IL1B, IL6, and TNFA genes were the most replicated and relevant in depression." (PMID 37510364, 2023). "Inflammation was an important cause of depression, and increased inflammation cytokines was related to depression, particularly IL-1β." (PMID 37293210, 2023). "On the contrary, co-morbid depression was mediated downstream of spinal cord IL-1β signaling and the formation of kynurenine and its metabolites in the brain." (PMID 36899845, 2023). "The evaluation of 292 individuals with major depression treated with fluoxetine for at least 6 weeks showed decreased levels of IL-1β, IL-6, or TNF-α at the end of the antidepressant treatment." (PMID 37242611, 2023). "Various studies have shown that increased levels of TNFα, IL1β and IL 6 are detected in patients with major depression, BD, schizophrenia and other psychiatric diseases." (PMID 36676137, 2023). "According to previous studies, central nervous system alterations induced by inflammatory cytokines (such as IL-1β and TNF-α) cause behavioral changes like fatigue and symptoms like depression." (PMID 38444713, 2023). "The study showed a bidirectional relationship between depression and sleep disorders, and a significant effect of depression and sleep disorders on IL-6 and IL-1β." (PMID 37509542, 2023). "Spared sciatic nerve injury-induced pain, memory deficits and depression-like behaviors were prevented by the peri-sciatic administration of IL-1β neutralizing antibodies in rats." (PMID 36982563, 2023). "TNF-α, IFN- α, IL-1, IL-1β and IL-6 are mostly found with increased concentrations in the serum of depression and anxiety patients." (PMID 37764111, 2023). "The assessment of hypothalamic inflammatory responses induced by LPS stress involved the detection of the three inflammatory cytokines TNF-α, IL-1β, and IL-6 that play crucial roles in the pathogenesis of depression." (PMID 38062440, 2023). "There is much research dedicated to studying the contribution of IL1B-511C/T in the pathogenesis of depression disorders." (PMID 37510364, 2023). "IL-1β, along with IL-6 and TNF, has been linked to sickness behavior and implicated in depressive disorders." (PMID 37762207, 2023). "The first study was published twenty years ago, and it has been reported recently that patients suffering from depressive disorder are characterized by increased concentrations of IL-1β, IL-6, and TNF-α compared to controls." (PMID 37834806, 2023). "Evidence has suggested that the P2X7 receptor (P2X7R), NLRP3, and IL-1β play an important role in depressive disorder." (PMID 36979246, 2023). "In diabetes, the development of depressive disorder is related to hyperglycemia and an increase in the circulating pro-inflammatory cytokines IL-1β, IL-6, and TNF-α, known as low-grade inflammation." (PMID 37892186, 2023). "In several models of depression, the expressions of inflammatory cytokines such as Tnfα, Il1b, and Il6 in the hippocampus were increased and higher microglial activation in the hippocampus was observed compared with controls." (PMID 36151082, 2022). "In breast cancer patients, positive correlations have been observed between depression and inflammatory markers, such as IL-1β, IL-6, and tumor necrosis factor-alpha (TNF-α)." (PMID 36615742, 2022).
depression (continued). "Much of the interest in inflammation and depression has been focused on cytokines that mediate the innate immune response, such as interleukin-1beta (IL-1β)." (PMID 35939172, 2022). "Depression-like behaviors are related to increased peripheral blood levels of IL-1β, IL-6, TNF, and CRP, the most reliable biomarkers of inflammation." (PMID 36278007, 2022). "Several inflammatory markers, namely interleukin-1β (IL-1β), IL-6, and C-reactive protein (CRP), are associated with depression." (PMID 36188478, 2022). "Pre-clinical studies focusing on different chronic pain models with comorbid depression also reported upregulation of IL-1β, IL-6 and TNF-α." (PMID 35733107, 2022). "Th17 cells participate in depression, which is activated by several cytokines, such as IL-1β, TNF-α, and IL-6." (PMID 35054853, 2022). "NLRP3, caspase-1, ASC, IL-6, and IL-1β in this signaling pathway are closely related to inflammation and depression." (PMID 36556951, 2022). "Of note, the correlations of TNF‐α and IL‐1β with depression were more obvious compared with IL‐6 and IL‐17." (PMID 34697903, 2022). "Previous studies with major depressive disorder, schizophrenia, and generalized anxiety disorder showed that higher levels of IL-1β, IL-2, IL-6, and CCL2 were related to the severity of psychiatric symptoms." (PMID 35504954, 2022). "Serum TNF‐α, IL‐1β, IL‐6, and IL‐17 are related to increased anxiety and depression risks to some extent in NSCLC survivors." (PMID 34697903, 2022). "A meta-analysis concluded that IL-1β was significantly elevated in patients with depression and Alzheimer’s disease (AD), while IL-6 was elevated only in patients with depression." (PMID 36614020, 2022). "For example, intravenous or subcutaneous IL-1β injection increased depression-like behavior in mice and enhanced the expression of pro-inflammatory cytokines TNF-α and IL-6 in the amygdala, which is regulated by the CORT/GR system." (PMID 36232376, 2022). "NLR3P inflammasome cleavage of pro-caspase 1 into caspase 1 results in the production of IL1-β from these activated microglia in situations of neuroinflammation such as in depression." (PMID 35782423, 2022). "Clinical depression has been shown to be accompanied with an increase in the pro-inflammatory cytokine, interleukin, such as IL-1b and IL-6." (PMID 36140263, 2022). "The immune effects of IL-1β, IL-4, IL-10 and IL-8 in depression or PTSD have also been reported by other authors." (PMID 35326343, 2022). "Patients with depression have increased pro-inflammatory cytokines in the blood, such as interleukin-6 (IL-6), interleukin-1β (IL-1β), tumor necrosis factor-α (TNF-α) and other acute-phase proteins and C-reactive protein (CRP)." (PMID 36357867, 2022). "Inflammatory cytokines, such as IL-1β, are histologically damaging to oligodendrocytes and can lead to histological changes such as white matter lesions found in patients with depression." (PMID 35280153, 2022). "We observed elevated IL-1β, IL-6 and reduced IL-10 in the reserpine-induced hyperalgesia and depression comorbidity model group in our present study." (PMID 35733107, 2022). "This meta-analysis included 22 eligible studies of 827 patients with major depressive disorder (MDD): seven studies for IL-1β, 15 for IL-6, 11 for TNF-α, six for IL-4, and four for interferon-γ." (PMID 35280153, 2022). "To conclude, serum TNF‐α, IL‐1β, and IL‐17 levels are highly expressed, which are closely related to elevated anxiety and depression risks to some extent in NSCLC survivors." (PMID 34697903, 2022). "The current study also revealed that serum TNF‐α, IL‐1β, IL‐6, and IL‐17 were positively correlated with anxiety and depression risks in NSCLC survivors." (PMID 34697903, 2022). "Consistently, our study found that IL-1β expression as well as anxiety and depression-like behavior of rats were increased in TNBS group compared to the control group, but reversed by EA treatment." (PMID 35087621, 2022).